CD28 (CD28 molecule)
Diseases named in the same sentence as CD28 in open-access papers (continued):
Sharing a sentence is not in itself a finding about the gene and the disease.
cancer (continued). "Here we described the use of a new bi-specific aptamer to target CD28 costimulation to cancer stem cells, which are the key players in chemotherapy resistance." (PMID 26992239, 2016). "This difference resulted from the significantly lower proportion of CD28+CD57- cells among the stage IV cancer patients compared with the controls." (PMID 26711627, 2015). "This suggests that the NKG2D/CD28 modification may help maintain antitumor responses and mitigate T cell exhaustion, supporting its potential for further exploration in cancer immunotherapy." (PMID 40181405, 2025). "Taken together, these T-cell and cancer-cell binding results suggest that XmAb808 sequentially engages its two targets, first by avid and high-affinity binding to B7-H3, followed by binding to CD28, to form an artificial immunologic synapse between T cells and B7-H3+ cancer cells." (PMID 39301613, 2025). "Further, enhance T-cell activities via CD28 against HER2 positive cancer cell." (PMID 40918454, 2025). "Costimulatory receptor molecules that mediate the signalling transduction pathways of T-cell proliferation, differentiation and activation, such as cluster of differentiation 27 (CD27) and 28 (CD28), have been proposed as important immunomodulation targets in cancer treatments." (PMID 40038352, 2025). "The observed increase in mutation load in the low-risk group, alongside the elevated expression of immune checkpoint markers such as CD24, CD28, CTLA-4, and TIGIT in the high-risk group, underscores the complex interplay between genetic mutations and immune escape mechanisms in cancer development." (PMID 40510341, 2025). "This reduction in CD28 expression could also be due to immunosenescence, further contributing to an immunosuppressive environment that facilitates cancer initiation." (PMID 40143377, 2025). "The PPGK1-CD19 design activated the CAR T cells in a manner analogous to NALM6 across all examined target-to-effector cell ratios, hence verifying successful yeast-based simulation of CD19+ cancer cells towards the clinical Hu19-CD8ɑ-CD28-CD3ζ CAR T cell product." (PMID 41271729, 2025). "However, CTLA-4 affinity for these ligands is higher than CD28, therefore cancer cells tend to overexpress CTLA-4, consequently inhibiting T-cell-mediated immune responses." (PMID 39866237, 2025). "This increased CD28 engagement enhances T-cell activation and proliferation, strengthening the immune response against cancer cells and enabling T-cells to more effectively target cancer cells." (PMID 40130115, 2025). "Given that CD86, as a co‐stimulatory molecule, interacts with CD28 for T‐cell activation and survival, the loss of CD86 expression in TAM Macro‐2 may result from a cancer cell‐induced program in the PCa microenvironment." (PMID 38483933, 2024). "Previously, we mentioned GPX4’s research on cancer; in a new study, it was found that the loss of GPX4 leads to an excessive buildup of lipid peroxides and ferroptosis in Treg cells when T cell receptor/CD28 co-stimulation occurs." (PMID 38962561, 2024). "However, CD28 expression is frequently lost in exhausted T cells and during immune senescence, limiting the clinical benefits of PD-1 ICIs in individuals with cancer." (PMID 39634262, 2024). "Then, the human peripheral blood T lymphocytes were co-cultured with cancer cells (F2-H3) supplying the CD28 signal for 48 h, and subsequently the T-cell repertoire was separated into targeted activation group (T-F2-H3) and non-targeted group (T-control) by flow cytometry sorting." (PMID 39158647, 2024). "Several studies reported the roles of soluble CTLA-4 and CD28 in cancer screening." (PMID 39218939, 2024). "CTLA-4 and CD28 can bind to B7-1 or B7-2 on the surface of cancer cells." (PMID 39682188, 2024). "Recent data indicated that CD80 or CD86 expressed on cancer cells could enhance BiTE cytotoxicity in vitro by signaling through CD28, as does concomitant use of monoclonal CD28 antibodies." (PMID 39473905, 2024).
cancer (continued). "To develop novel anti‐cancer approaches, we constructed a chimeric antigen receptor construct using a high binding and codon optimised scFv‐IL‐13Rα2 fragment fused with CD3ζ and co‐stimulatory cytoplasmic domains of CD28 and 4‐1BB." (PMID 38685487, 2024). "CD28 signaling is impaired in cases of chronic infection and cancer." (PMID 37582972, 2023). "For example, the sensitivity hierarchy that we observe [STARS > TruCs > CAR (CD28 hinge) > CAR (CD8a hinge) > CAR (IgG1 hinge)] suggests that standard CARs may be preferred for targeting cancers that overexpress antigens also expressed on normal cells." (PMID 36598945, 2023). "For example, the development of CD28 blockers may allow for more targeted cancer therapy by interrupting the activation and development of Treg cells." (PMID 37828948, 2023). "Furthermore, both in vitro CD3/CD28 activation and incubation with cancer cells conditioned medium, was enough to induce the expression of TMEM123 in peripheral T cells." (PMID 37426665, 2023). "As a member of the CD28 and B7 families, CD276 inhibits T-cell function, and is highly expressed in numerous types of tumor, so it is often associated with poor prognosis and shorter survival rates in cancer patients." (PMID 36717836, 2023). "In addition to dephosphorylation by PD-1, CTLA-4 at high levels in the chronic infection or cancer context competes for the ligands of CD28, namely, B7 family receptors, thereby diminishing CD28 signaling." (PMID 37582972, 2023). "However, when CD28 binds to CTLA-4 on a cancer cell (which has a greater affinity for CD28 than CD80 or CD86), T cells become depleted, anergic and killed." (PMID 35741450, 2022). "CAR T1E-engineered NK-92 cells, harboring the sequence of T1E single-chain fragment variant (scFv) to recognize the ErbB receptor, bearing either CD28 or 4-1BB as co-stimulatory signaling domains, were prepared and assessed for their effectiveness in two different ErbB(+) cancer cell lines." (PMID 36359405, 2022). "For both blood and cancer tissues the HLA-DR− cells suppressed anti-CD3/CD28 stimulated T cells." (PMID 34727230, 2022). "Moreover, we found that cancer survivors in our study had significantly higher expression of CD28 and lower expression of CD57 on T cells than age matched controls." (PMID 33605556, 2021). "CAR T cells containing the CD28 molecule could improve anti-cancer functions and persistence both in vitro and in vivo compared to first-generation CAR and 4-1BB-based CAR T cells." (PMID 33737613, 2021). "Blocking CD28 with antibodies on human T cells or using T cells from PD1−/− and CD28−/− mice showed that sB7-1-mediated anti-cancer immunity was not only dependent on neutralizing PD-1/PD-L1-mediated immune suppression but also a simultaneous B7-1-CD28 co-stimulation." (PMID 34531847, 2021). "In addition, CMV seropositivity and CD57+CD28– CD8 T cells have been correlated with cancer and heart disease after kidney transplantation." (PMID 34122420, 2021). "In contrast, the expression of genes regulating immune cell trafficking (e.g., CXCL13, CXCL9, XCL2, CCL5), T-cell activation and clonal expansion (e.g., CD27, CD28, ICOS, IL21, IL2) were massively decreased in 9p21-loss tumors across multiple cancer types/subtypes." (PMID 34556668, 2021). "In our study, advance cancer stage was negatively associated with levels of B cells, CD4+ T cells, naïve CD4+/CD4+, naïve CD4+ T cells, CD4+CD28+ T cells, CD8+CD28+ T cells and positively associated with NK cells, WBC counts, monocytes, neutrophils, eosinophils, basophils, MLR, NLR, ELR, BLR, PLR." (PMID 34488711, 2021). "MiRNA MIR17 with low expression could negatively regulate target genes BECN1 and CD28 to promote the proliferation of cancer cells and inhibit autophagy, apoptosis, and the immune response." (PMID 33802957, 2021).
cancer (continued). "Moreover, the discovery of CD4/CD8-p56lck and its targets ITAMs and CD28 has led to the application of this knowledge in the design on CARs presently in use in cancer immunotherapy." (PMID 33791292, 2021). "Moreover, there were several autoimmune diseases and cancers simultaneously associated with CTLA-4 and CD28 genes." (PMID 32210155, 2020). "Similarly, there was extended PFS in other cancer patients with high expression of CD28 or low exosomal PD-L1 value (medianCD28, 2 vs. 9.2 months, P = 0.045; median PD−L1, 2 vs. 7.3 months, P = 0.066)." (PMID 32528882, 2020). "We found that, at least in a human cancer setting, the expression of CD57 on senescent Vδ2pos T cell parallels their terminal differentiation towards TEMRA (CD27neg/CD45RApos), a phenomenon associated with the loss of CD28 and the acquired expression of CD16." (PMID 31829255, 2019). "B7 can bind to CD28 to promote T-cell proliferation and kill cancer cells." (PMID 32793247, 2018). "As a result, CD28 cannot promote T-cell activation to inhibit proliferation of cancer cells." (PMID 32793247, 2018). "Pro-inflammatory cytokines present in the media, including IL-2 and CD3/CD28 beads, may have contributed to untransduced T cell activation, leading to granzyme and perforin release and detectable cancer cell death." (PMID 29255242, 2017). "These included genes involved in cell death and survival processes (BCLAF1, CFLAR, CASP1, and XIAP), genes associated with proliferation-driving transcription or cancer (KLF4, LEF1, SOX4, ID3), and genes associated with inflammation (CD28, CCR7, CX3CR1 and IFNG)." (PMID 28407008, 2017). "Adoptive transfer of TILs possessing properties of less differentiated T cells, such as high surface expression of the costimulatory molecules CD28 and CD27 and long telomeres (>5 kb), is associated with their increased persistence in vivo and correlates with objective cancer regression." (PMID 21827675, 2011). "Furthermore, CD28 in cancer cells promotes PD-L1 expression, which suppresses T cell activity." (PMID 41155258, 2025). "Collectively, these findings underscore the necessity of CD28 co-stimulation for rescuing CD8+ T cells, highlight the critical role of the CD28/B7 pathway in PD-1 therapy for cancer patients, and suggest that increased expression of CD28 on PD-1+ CD8+ T cells may indicate a better response to ICIs." (PMID 40385461, 2025). "Senescent T cells exhibit abnormal phenotypes, including downregulation of costimulatory molecules such as CD27 and CD28, and upregulation of killer cell lectin‐like receptor subfamily G, CD57, Tim‐3, and cytotoxic T‐lymphocyte‐associated protein 4, which are closely related to malignant tumors." (PMID 38660685, 2024). "We hypothesized to produce a powerful immune response against solid tumors by combining the antibody redirected cancer cell targeting, the CD28-CD3ζ triggered T cell activation through a CAR, and the repetitive restimulation of the retargeted T cells by engaging the endogenous B cells." (PMID 36672182, 2023). "Thus, the elevation of CD4+CD28+T cells might imply an upregulated antitumor immune response due to the influence of cancer." (PMID 37346066, 2023). "In addition, the bispecific antibodies redirecting the T cells towards the antigen-presenting cells and augmenting their activation by enhancing the B7/CD28 co-stimulation, may allow for establishing a more durable anti-cancer immune response." (PMID 36672182, 2023). "The development of CD28 blockers could potentially offer a more targeted therapy for cancer." (PMID 37828948, 2023). "Therefore, one of the effects of therapeutic monoclonal antibodies targeting CTLA-4 (interacting with CD28) and PD-L1 (interacting with PD-1), is allowing T-cells to maintain their increased glycolytic and glutaminolytic capacity to execute anti-cancer effector functions in the TME." (PMID 35070990, 2021).
cancer (continued). "In this work, anti-CD3 and anti-CD28 were responsible for mimicking dendritic cells to activate T cells, and anti-PD-1 for blocking the pathway of PD-1/PD-L1 to break the immune “brake”, which synergistically regulated the behavior of T cells to attack cancer cells." (PMID 35059157, 2021). "In addition, the ELISA results showed an increase of IFN-γ secretion upon anti-CD3/anti-CD28 stimulation (Left) and the lymphocyte-mediated cytotoxicity against cancer cell assay demonstrated an enhanced cancer cell killing effect of CD8+ T cells from Rab37 KO mice (Right)." (PMID 34093869, 2021). "Senescent T cells exhibit abnormal phenotypes, including downregulation of CD27, CD28, and upregulation of CD57, killer cell lectin-like receptor subfamily G, Tim-3, Tight, and cytotoxic T-lymphocyte-associated protein 4, which are tightly related to malignant tumors." (PMID 33168037, 2020). "On the other hand, the use CD28 agonists to awaken T cells from the tolerant state could lead to new therapies to re-activate the immune system for the treatment of infectious disease and cancer." (PMID 31181772, 2019). "Given that the expression of CD27 and CD28 are unchanged and the reduced functionality is true for the whole population, we do not believe that the reduction of functionality is due to a classical exhaustion process as the ones observed in chronic viral infections and cancer." (PMID 29176779, 2017). "As a homolog of CTLA-4, CD28 may also contribute to the development of cancer." (PMID 23133541, 2012). "Among 60 ICP genes, including 24 immune inhibitors (such as CTLA4, LAG3, or VEGFB) and 36 activators (TNFRSF9, CD28, or TNFRSF9, etc.), we found DHCR7 played roles both in inhibitors and activators of ICP in human cancers." (PMID 41198144, 2025). "recently reported that PD-1/PD-L1 cancer immunotherapy also necessitates CD28 co-stimulation for CD8 T cell rescue, highlighting the crucial role of the CD80/CD28 pathway." (PMID 40746567, 2025). "The B7/CD28 family of molecules, comprising several immune checkpoint proteins and their receptors, such as CD28, CTLA4, PDCD1, etc. have gained considerable attention in the field of cancer therapy." (PMID 40808941, 2025). "Thus, loss of costimulation through CD28 may not impact effector CD8 T cell control of residual cancer cells following radiation." (PMID 41417245, 2025). "This therapeutic approach requires that cancer cells express both antigens targeted by the CD3 and CD28 bispecific antibodies." (PMID 39301613, 2025). "We therefore assessed the secretion of IFN-γ following incubation with various cancer cells including Raji, Nalm6, K562-CD19, K562-CD22, CD3 + /CD28 + T cells, and K562." (PMID 40719826, 2025). "Analysis of cluster-specific genes indicates that these clusters correspond to cancer cells (GFP, Crabp1, Ank), myeloid cells (Aif1, Ctsc, Mpeg1), lymphoid cells (Il2rb, Cd28, Cd3e/g/d, Cd37), and stromal cells (Col1a1/2, Lum, Eln, Dpt), respectively." (PMID 41280683, 2025). "CD28 expression is predominantly expressed by CD4+ T cells and is higher in controls than precancer or cancer (p < 0.0001)." (PMID 39672307, 2024). "Several inhibitory immunoreceptors, including but not limited to CD28, CD80, CD86, CTLA4, CD276, and CD274, have been identified and studied in cancer in recent decades." (PMID 38831187, 2024). "To investigate the potential role of USP10 in facilitating immune escape by cancer cells, we utilized a co‐culture system with cancer cells and human PBMCs, activating cytotoxic T‐cells with anti‐human CD3 and CD28.2 antibodies." (PMID 39206932, 2024). "Research has shown that the reduction of CD28 expression is a characteristic feature of senescent CD8+ T cells, and CD28− senescent T cells exhibit immunosuppressive functions in cancer." (PMID 39678507, 2024).
cancer (continued). "Immune checkpoint therapy has shown considerable promise in treatment of cancers currently, many immune checkpoints are highly positively correlated with BAX, such as ENTPD1, CD80, and CD28." (PMID 39074253, 2024). "The expression of CD28 decreased in both cancer and precancer compared to the control group, while the expression of FLT3LG was decreased in cancer compared to precancer and controls." (PMID 39672307, 2024). "During the induction phase of the anti-cancer immune response, immune checkpoint molecules inhibit the activation of effector T cells by interfering with the interaction between CD80/CD86 and CD28." (PMID 39507618, 2024). "In the PD1 and PD-L1 cancer immunotherapy pathway, downregulation of CD247, PDCD1, and CD28 gene expression and upregulation of CD274 and miR-3614-5p were measured." (PMID 38571958, 2024). "The critical role of CD28 in this context underscores the complex interactions and finely tuned balances that dictate immune responses and ICB efficacy in cancer patients." (PMID 39684559, 2024). "The T cell markers CD28 and FLT3LG expression decreased in cancer while FOXP3, IDO1, and ULBP2 expression increased." (PMID 39672307, 2024). "The ARMG risk score showed significantly positive relation with immunoinhibitors TGFB1 and VTCN1, and was negatively related with immunostimulators CD27, CD28, CD40LG, CD80, ENTPD1 and ICOS in pan-cancer." (PMID 38090588, 2023). "Intriguingly, the expressions of TIGIT and CD28 were positively correlated with those of DDR1 in LAML and LIHC but negatively correlated with those of DDR1 expression in the other 17 cancers." (PMID 37031216, 2023). "Studies have shown that the PD1-recruited SHP2 phosphatase prefers to dephosphorylate the co-stimulatory receptor CD28, suggesting that CD28 expression is required for an effective anti-PD1 treatment response in cancer." (PMID 36763585, 2023). "T cells undergoing beta-selection differentiate via sequential expression of co-receptors CD28, CD5, and CD2, exposing new signalling controls that are disrupted by a cancer therapeutic." (PMID 36283704, 2023). "Several works support a strict correlation between the number of CD28− CD8+ T cells or CD57+ CD8+ T cells and cancer." (PMID 35328795, 2022). "In most cancers, CD86, TNFSF14, KLRK1, CD48, CD40LG, CD28, C10orf54, ENTPD1, CXCL12, and POLD2 are negatively correlated (p < 0.05)." (PMID 36081989, 2022). "Another indicator that shows PLAP CAR T cells are less differentiated than other groups is the high expression of CD27 and CD28 on PLAP CAR T cells, which can stimulate them against cancer cells." (PMID 36139135, 2022). "This CD28− CD8+ Foxp3+ subset, found in many cancers, has also been identified in the TME of GBM patients, and it amplifies the immunosuppression mediated by T regulatory (reg) cells, thus contributing to the dysfunction of dendritic cells (DCs)." (PMID 35328795, 2022). "Based on the fact that CD28-CAR-T cells are more potent in killing cancer cells, and 4-1BB-CAR-T cells exhibit lower depletion rates and longer-lasting killing effects on cancer cells, third-generation CARs added both CD28 and OX-40/4-1BB." (PMID 35911706, 2022). "CD127 and CD28 have been used as extracellular markers of TCF-1+ progenitor CD8+ T cells in chronic infections and cancer." (PMID 35584630, 2022). "DMSNs3@HA is a DC-like nanoparticle modified with hyaluronic acid to target CD44 overexpressed on cancer cells, and conjugated with anti-CD3, anti-CD28 to interact with T cell, and anti-PD-1 to block the PD-1/PD-L1 pathway." (PMID 35967869, 2022). "Correlations were observed between CREB3L1 expression and several immune biomarkers such as CD28, CXCR4 and KDR in several cancers." (PMID 36171879, 2022). "In fact, ICs pathways, more importantly, PD-1/PD-L1 and CD28/CTLA-4, are co-opted by tumors, altering expression of proteins to ease cancer cells' evasion from immune surveillance as a result of the inhibiting T cell responses." (PMID 36510217, 2022).